PPARG (peroxisome proliferator activated receptor gamma)
Diseases named in the same sentence as PPARG in open-access papers (continued):
Sharing a sentence is not in itself a finding about the gene and the disease.
Insulin resistance (continued). "When PPARγ expression in macrophages was ablated in mice, this resulted in systemic insulin resistance with attenuated insulin sensitizing effects of TZDs." (PMID 22529965, 2012). "Low-grade inflammation is considered to be an important mechanism in insulin resistance, and the lipid metabolic regulators PPARα, PPARγ, as well as PGC-1α have been shown to play a role in the regulation of insulin sensitivity." (PMID 23251491, 2012). "Peroxisome proliferator-activated receptor γ (PPARγ), a nuclear receptor, stimulates lipid uptake and adipogenesis by fat cells and is a key regulator of lipid metabolism, adipogenesis and insulin resistance." (PMID 23145084, 2012). "The peroxisome proliferator-activated receptor gamma (PPARγ) is a nuclear receptor highly expressed in adipose tissue but also intestine, playing a key role in regulation of insulin resistance and inflammation." (PMID 22997506, 2012). "Pioglitazone is a peroxisome proliferator activated receptor-gamma (PPARγ) agonist and represents a class of anti-diabetic agents that reduce insulin resistance mainly by activating PPARγ." (PMID 22920475, 2012). "The present study demonstrated that direct AT2 receptor stimulation by C21 accompanied with PPARγ activation ameliorated insulin resistance in T2DM mice, at least partially due to improvement of adipocyte dysfunction and protection of pancreatic β cells." (PMID 23155382, 2012). "Since NAFLD often leads to insulin resistance, this paper focuses on the relationship between Pparγ and NAFLD." (PMID 22966224, 2012). "PPARγ, a nuclear transcription factor, plays an important role in regulation of adipocyte differentiation, insulin resistance, and inflammation." (PMID 23155382, 2012). "In particular, PPARγ plays an important role in the regulation of lipid homeostasis, adipogenesis, insulin resistance, and in the development of various organs." (PMID 23213321, 2012). "The therapy used for insulin resistance frequently include the administration of TZDs which are agonists for the nuclear receptor peroxisome proliferator activated receptor gamma (Pparγ)." (PMID 22966224, 2012). "PPARγ activation results in increased sensitivity to the metabolic actions of insulin, partly by reversing lipotoxicity-induced insulin resistance." (PMID 22448165, 2012). "In this study, we investigated the effect of PPARγ and RBP4 polymorphisms on body mass, insulin resistance and dyslipidemia among HIV-infected patients with anti-retroviral therapy (HAART)." (PMID 23145084, 2012). "This suggested that inflammation is a component in developing insulin resistance in the mouse and macrophage PPARγ deletion exacerbated this inflammation." (PMID 21382489, 2011). "Because of these contradicting results further studies are needed to clarify the contribution of macrophage PPARγ to the development of insulin resistance." (PMID 21382489, 2011). "We found that A. indicum L. ameliorates insulin resistance via PPARγ activation and enhances glucose uptake." (PMID 21603234, 2011). "Recent data suggest that activation of PPARγ by using plant extracts improves lipid metabolism and mitigates insulin resistance." (PMID 21603234, 2011). "It is well known that PPARγ has a wide range of actions on glucose homeostasis and metabolism, and many exogenous PPARγ agonists have been used to treat type 2 diabetes and insulin resistance." (PMID 21664456, 2011). "Here we have investigated PPARγ dependent transcriptional responses occurring during the early stages of beta cell adaptation to insulin resistance in wild type, ob/ob, PPARγ2 KO and POKO mice." (PMID 22208362, 2011). "Expression of the PPARγ gene in muscle tissue was lower in HIV-infected subjects with insulin resistance (HIV-IR group) compared to uninfected subjects (control) by simple t-test (P = .03)." (PMID 21559208, 2011). "The capacity of TZDs to ameliorate insulin resistance is typically attributed to their ability to activate PPARγ and promote adipogenesis." (PMID 22087241, 2011).
Insulin resistance (continued). "Thiazolidinediones are a class of Peroxisome Proliferator Activated Receptor γ (PPARγ) agonists that reduce insulin resistance in type 2 diabetic patients." (PMID 20981297, 2010). "Pharmacological activation of PPARγ ameliorates insulin resistance in diabetes, and has been reported to decrease liver damage in NAFLD by restoring adipose tissue insulin sensitivity, thus decreasing FFAs flux to the liver." (PMID 20825652, 2010). "Activating synthetic ligands for peroxisome proliferator-activated receptor gamma (PPARγ), such as pioglitazone, are commonly used to treat persons with diabetes mellitus with improvement of insulin resistance." (PMID 20814432, 2010). "PPARγ can also affect insulin sensitivity by regulating hormones, cytokines, and proteins that are involved in insulin resistance." (PMID 20981297, 2010). "A commonly used strategy to alleviate tissue insults and restore cellular metabolism in conditions of elevated inflammation and insulin resistance is PPARγ agonists." (PMID 20508722, 2010). "TZDs, synthetic ligands of PPARγ, such as rosiglitazone and pioglitazone, have already been introduced into clinical practice for the treatment of insulin resistance." (PMID 20613959, 2010). "PPARγ activation promotes adipogenesis, fatty-acid storage, and eventually obesity, insulin resistance, and type 2 diabetes." (PMID 20825652, 2010). "It has been reported that internal PPARγ mediates adipocyte hypertrophy and insulin resistance under long term high fat (beef tallow) diet." (PMID 20846400, 2010). "Activated synthetic ligands for PPARγ are widely used as treatment for type 2 diabetes mellitus (DM) in order to improve insulin resistance." (PMID 20814432, 2010). "The thiazolidinediones – or glitazones for short – decrease insulin resistance in muscle and adipose tissue by activating the peroxisome proliferator-activated receptor-gamma (PPAR- gamma) which increases production of proteins involved in glucose uptake." (PMID 19568428, 2009). "They activate PPARγ and decrease insulin resistance and glucose level in the serum of patients with type 2 diabetes." (PMID 20182551, 2009). "Lipodystrophy syndromeassociated with insulin resistance plays a role in the development of fatty liver disease.By enhancing insulin sensitivity, PPARγ agonists or thiazolinediones are used for thetreatment of type 2 diabetes." (PMID 19390649, 2009). "Studies in rodents suggest that activation of hepatic PPARγ signaling promotes lipid accumulation in the liver, and hepatic expression of PPARγ is elevated in rodent models of diabetes and insulin resistance that exhibit liver steatosis." (PMID 20182551, 2009). "To date, thiazolidinediones (TZDs), PPARγ agonists, are some of the more effective treatments used for improvement of insulin resistance." (PMID 19589179, 2009). "Rosiglitazone, a synthetic agonist of the peroxisome proliferator-activated receptor gamma (PPAR gamma), is applied as the treatment of insulin resistance including women with PCOS." (PMID 20003221, 2009). "In the muscle, the prevention of insulin resistance in rats supplemented in fiber has been explained by the effect of butyrate increasing GLUT-4 via PPARγ." (PMID 18847460, 2008). "Genetic interference with regulators of inflammatory pathways, such as IKKβ and PPARγ, in myeloid derived cells has also been demonstrated to confer partial protection from insulin-resistance." (PMID 18773087, 2008). "Beside beneficialeffects of TZD therapy in insulin resistance, edema and water retention alsofrequently occurs as secondary effects of PPARγ activation." (PMID 19283081, 2008). "In the case of the TZD class as PPARγ agonists, the major side effect is weight gain.A Pro12Ala substitution in PPARγ2 decreasesPPARγ activity, BMI, and insulin resistance." (PMID 18566691, 2008). "Arsenite also inhibited the differentiating effect induced by pioglitazone, a PPARγ agonist used to reduce insulin resistance." (PMID 16675414, 2006).
Insulin resistance (continued). "It is well known that circulating adiponectin increases insulin sensitivity, is decreased in T2D patients, and is negatively correlated with insulin resistance; PPARγ agonists increase insulin sensitivity as well as circulating adiponectin." (PMID 15491498, 2004). "PPARγ agonists also alleviate peripheral insulin resistance in humans, and have been effectively used in treatment of T2D patients." (PMID 15491498, 2004). "The current study showed that PPARγ agonists increased serum levels of adiponectin, ameliorated insulin resistance and lipid profile in both diet-induced insulin resistant rats and ZDF rats." (PMID 15491498, 2004). "Adipose tissue-derived EVs impair hepatic fatty acid oxidation, promote steatohepatitis, suppress pancreatic beta-cell insulin secretion, induce skeletal muscle insulin resistance via PPARγ repression, and contribute to endothelial dysfunction and atherosclerosis." (PMID 41977323, 2026). "Our findings suggest that these FAs may modulate PPARγ activity through mechanisms involving stearoyl‐CoA desaturase 1 (SCD1), an enzyme implicated in lipid metabolism and insulin resistance." (PMID 40968591, 2025). "In addition, PPARγ alleviates insulin resistance by modulating inflammation; mice with macrophage-specific PPARγ deletion exhibit impaired alternative macrophage activation, leading to insulin resistance and glucose intolerance." (PMID 41438090, 2025). "Because BMI is a coarse measure of metabolic status, factors such as insulin resistance, adipose distribution, inflammation, or diet quality may better reflect PPARG-related metabolic variance." (PMID 41282094, 2025). "However, lansoprazole has shown potential in reducing insulin resistance by increasing the expression of peroxisome proliferator-activated receptor gamma and CCAAT/enhancer-binding protein alpha mRNA in adipogenesis." (PMID 40459644, 2025). "Upon delivery to endothelial cells or macrophages, exosomal miR-155 can promote a pro-inflammatory phenotype and contribute to insulin resistance through modulation of peroxisome proliferator-activated receptor gamma (PPARγ) pathways, exacerbating vascular inflammation." (PMID 41267869, 2025). "In previous studies, we demonstrated that the pan-PPAR agonist 1d improves insulin resistance in T2DM mice by inhibiting PPARγ Ser273 phosphorylation in white adipose tissue and modulating the expression of genes such as adiponectin, without inducing weight gain or fluid retention." (PMID 41303582, 2025). "Moreover, PPARG is an important regulatory factor in glucose and lipid metabolism that can improve insulin resistance and enhance the sensitivity of target organs to insulin; thus, PPARG has a role in lowering blood sugar." (PMID 40417668, 2025). "Furthermore, macrophage−specific inactivation of PPARγ has been shown to amplify systemic inflammatory signaling, promote ectopic lipid accumulation, and worsen insulin resistance, underscoring the broader metabolic influence of macrophage−expressed PPARγ." (PMID 41476922, 2025). "Conversely, a study on human adipocytes indicated that Metrnl overexpression may inhibit PPARγ expression, potentially leading to hyperinsulinemia and insulin resistance." (PMID 40559404, 2025). "Given the close link between NAFLD, insulin resistance, and abnormal lipid metabolism, thiamine’s effects on PPARγ and its antioxidant properties may help reduce hepatic steatosis and inflammation." (PMID 41368574, 2025). "Atrazine and 2,4-D have been linked to endocrine disruption through interference with estrogenic and thyroid pathways, activation of PPARγ—a transcription factor central to fat storage and adipocyte differentiation—and mitochondrial dysfunction, leading to insulin resistance." (PMID 41150593, 2025). "Similarly, long-term use of PPARγ agonists can result in receptor downregulation and secondary insulin resistance, making the treatment less effective over time." (PMID 40926269, 2025).
Insulin resistance (continued). "Thus, PPARγ can regulate adipose tissue remodeling and attenuate insulin resistance and dyslipidemia." (PMID 40137162, 2025). "Furthermore, compounds that inhibit cdk5‐mediated PPARγ Ser273 phosphorylation have shown promise in reducing insulin resistance." (PMID 40994455, 2025). "Moreover, FLRE and FLLE remarkably reduced chemoattractant (MCP-1) but improved adipogenic (PPARγ and CEBPα) gene expression, leading to the promotion of adipogenesis and the suppression of insulin resistance." (PMID 38543073, 2024). "Inactivation of PPARγ in the embryo but not in trophoblasts caused severe lipodystrophy, organomegaly, and insulin resistance, whereas glucose tolerance was decreased in male and increased in female mice." (PMID 38727299, 2024). "Increased serum levels of free fatty acids (FFAs) in obese individuals promote vascular endothelial growth factor A (VEGF-A) and vimentin expression through peroxisome proliferator-activated receptor gamma (PPARγ) upregulation, contributing to tumor growth, insulin resistance, and hepatic steatosis." (PMID 38534735, 2024). "Additionally, other mRNA molecules target PPARγ and contribute to insulin resistance, such as miR-155 and miR-29 secreted by adipose tissue macrophages (ATMs)." (PMID 38790954, 2024). "The authors also reported that pomegranates prevented the increase in insulin and insulin resistance and regulated lipid metabolism while canceling the reduction in mRNA expression of peroxisome proliferator-activated receptor gamma (PPARγ) in hepatic tissue induced by CAF." (PMID 39204642, 2024). "The PPARγ-mediated adjustment of the balance of glycolipid metabolism and the improvement in insulin resistance may be key measures for the prevention and treatment of NAFLD with celastrol." (PMID 38276299, 2024). "Specific miRNAs derived from adipose tissues, such as miR-222, miR-27a, and miR-130b, which are increased in the serum of obese humans and mice, have been shown to induce insulin resistance in the skeletal muscle or liver respectively by targeting insulin receptor substrate 1, PPARγ, and PGC-1α." (PMID 39872218, 2024). "3-Hydroxybutyrate, originating from the increased β-oxidation of free fatty acids, is found in higher concentrations in the plasma of T2DM patients and has been shown to ameliorate insulin resistance in T2DM mice through the HCAR2/Ca2+/cAMP/PKA/Raf1/ERK1/2/PPARγ pathway." (PMID 38184583, 2024). "Furthermore, the first gene to respond to changes in the DNA methylation profile due to high-fat diet-induced insulin resistance in adipocytes was PPARG." (PMID 39595621, 2024). "Similarly, the genetic polymorphisms in different genes such as CAMK2, IGF1, IRS1, GCKR, PPARG, GCK1, and KCTD1 are found associated with insulin resistance and T2DM." (PMID 37829557, 2023). "In addition, the PPARγ agonists rosiglitazone reverses cognitive dysfunction by improving the peripheral insulin resistance in rats with high-fat diet." (PMID 37575299, 2023). "The pathway of 3HB/HCAR2/Ca2+/cAMP/PKA/Raf1/ERK1/2/PPARγ might be the molecular mechanism by which 3HB ameliorates insulin resistance." (PMID 37230992, 2023). "PPARγ is a major transcription factor that modulates both glucose and lipid metabolism, and its expression in adipose tissue is associated with HFD-induced adipocyte hypertrophy and insulin resistance." (PMID 36729332, 2023). "Peroxisome proliferator-activated receptor-gamma (PPAR-γ) agonists are insulin-sensitising drugs designed for diabetes patients with insulin resistance; furthermore, they can regulate several cellular processes, such as Aβ degradation and the anti-inflammatory response." (PMID 36830783, 2023). "Furthermore, PPARγ agonists reduce hyperinsulinemia/insulin resistance, by modulating the expression of inflammatory cytokines and adipokines that affect muscle and hepatic metabolism and overall insulin sensitivity." (PMID 37893070, 2023).
Insulin resistance (continued). "PPARγ Ser273 phosphorylation has been shown to play a critical role in insulin resistance." (PMID 36841479, 2023). "PPARγ is the main type of PPAR in adipose tissue, and is a major target for drug development in T2D,22,23 suggesting that 3HB could act as an insulin resistance reduction agent through PPARγ signaling pathway." (PMID 37230992, 2023). "This phosphorylation of PPARG dysregulates the expression of numerous PPARG-regulated genes, including the gene ADIPOQ coding for the key in vivo insulin-sensitizing adipokine adiponectin, and has therefore been linked to the development of insulin resistance." (PMID 37555665, 2023). "The mechanism of DM protection against T2DM-NAFLD is to improve liver function and pathological morphology by promoting peroxisome proliferator-activated receptor γ (PPARγ) activation, lowering blood glucose, improving insulin resistance (IR), and reducing inflammatory factors." (PMID 36874030, 2023). "Therefore, 3HB significantly regulated the expression of PPARγ downstream genes which were affected by Ser273 phosphorylation at both gene transcription and protein translation levels, resulting in reducing of insulin resistance level." (PMID 37230992, 2023). "Drugs such as rosiglitazone that potently and directly activate PPARG are believed to treat insulin resistance in part by promoting adipogenesis and fat cell function, but they have side effects since PPARG is critical in other differentiation and regulatory processes in different tissues." (PMID 36469503, 2022). "We have known that PPARs which are transcription factors belonging to the nuclear receptor superfamily control expression of various genes that are crucial for lipid and glucose metabolism, and adiponectin were stimulated by PPARγ activation, improving insulin resistance and glucose homeostasis." (PMID 35603780, 2022). "The authors further found that Gm15290 regulated miR-27b, a miRNA that played important roles in both adipocyte differentiation and adipocyte insulin resistance through targeting insulin receptors and PPARγ, to promote PPARγ-induced fat deposition in WAT, resulting in body weight gain in mice." (PMID 36555704, 2022). "In adipose tissue, PPARG deletion leads to lipoatrophy and insulin resistance (IR)." (PMID 35207731, 2022). "Additionally, we validated the hypoglycemic effects of morusin on repressing the expression of the ADORA1 and PPARG genes to improve insulin resistance in L02 cells." (PMID 36278175, 2022). "SIRT1 gain-of-function mimics the PPARγ activation in alleviating insulin resistance." (PMID 35743009, 2022). "Animal studies have shown that PPARG protects from high-fat diet-induced insulin resistance." (PMID 37192883, 2022). "Peroxisome proliferator-activated receptor (PPARγ) activates some genes in tissues that result in an increase in glucose and lipid uptake, decreases free fatty acid concentration, and subsequently decreases insulin resistance." (PMID 36558918, 2022). "However, there are advantages to partial PPARγ activation, mostly brought about by elevated adiponectin levels and lower insulin resistance." (PMID 36552725, 2022). "Therefore, the activation of EBP changes the expression of Pparγ, which is in line with the research conducted by Blaise on the development of Pparγ-dependent insulin resistance." (PMID 34374904, 2022). "It is also worth noting that c-Src kinase was shown to directly phosphorylate PPARγ at Tyr78, and inhibition of it may aggravate insulin resistance and proinflammatory genes in adipose tissue." (PMID 36551260, 2022). "However, glucose homeostasis and lipid metabolism, which mainly occurs in the muscles, are the major mechanisms of PPARγ involved in the improvement of insulin resistance." (PMID 35603780, 2022).